IL17A (interleukin 17A)
Diseases named in the same sentence as IL17A in open-access papers (continued):
Sharing a sentence is not in itself a finding about the gene and the disease.
infection (continued). "Among the Th17-related signaling pathways, ‘Th17 Activation Pathway’ and ‘Differential Regulation of Cytokine Production in Macrophages and T Helper Cells by IL17A and IL17F’ were commonly activated in canine PBMCs at all times of infection." (PMID 33520738, 2020). "Our results show that the relative transcription levels of IL-17A, IL-22, IL-6, IL-1β, IFN-γ, and TNF-α increased at 5 and 12 days post H9N2 AIV infection, and these results are consistent with our previous research results and other reports." (PMID 33294434, 2020). "As expected, mice infected with Cr had increased colonic tissue expression of several cytokines associated with a pro-inflammatory Th1/Th17 immune response including IL-17A, IL-22, IL-6, IL-1β, TNF-α, and IFN-γ on day 12 after infection." (PMID 33076301, 2020). "Consistent with previous studies, IL-17A levels in the lung tissue and BALF were increased 8 h after infection and returned to the baseline by 24 h." (PMID 32229615, 2020). "In sharp contrast, IL-17A/F1, IL-17A/F2, IL-17C2, and IL-17D transcription was inhibited in the HK, while IL-17A/F1 and IL-17A/F3 did in the brain upon NNV infection." (PMID 32244562, 2020). "Neutrophils were depleted 2 days prior to IL-17A treatment and MCMV infection, then treated every other day after infection with anti-Ly6G or vehicle control." (PMID 31239384, 2019). "IL17F expression was higher than IL17A in this study (signal intensity of IL17A and IL17F: 51 and 218, respectively) and significantly up-regulated in infected macrophages after 9 hours of infection." (PMID 31725732, 2019). "Lung samples were also harvested from IL-17A knock-out and WT mice following infection with the PR8 virus to assess histological changes resulting from infection." (PMID 31681209, 2019). "Regarding the role of IL17A and IL17F in the immunity against infections, these cytokines seem to have redundant functions in the defense against Staphylococcus aureus, although both cytokines are necessary in the control of Citrobacter rodentium infection." (PMID 31616423, 2019). "Our study results show that IL-17A was mainly produced by Th17 cells in PBMCs from H7N9 patients in both the acute and recovery phases as well as at various time points in in vitro infection experiments." (PMID 31061831, 2019). "During P. aeruginosa infection, macrophages treated with IFN-γ or IL-17A displayed comparable levels of LDH release and active caspase-1 upon infection with P. aeruginosa, suggesting similar capacities to process pro-IL-1β." (PMID 30455194, 2019). "After infection of the H7N9 and H1N1(2009) viruses, both the protein and mRNA levels of IL-17A were decreased at all time points postinfection compared with mock-infected groups (respectively)." (PMID 31061831, 2019). "Spearman rank correlations between age, gender, IFN-γ, TNF-α, IL-10, IL-17A, ratio IFN-γ/IL-10, and exposure time in the infection place less or equal -and longer- than 90 days." (PMID 30186774, 2018). "CD4+ T cells isolated from the lungs of Nlrc3-/- mice showed stronger expression of intracellular IFN-γ, TNF-α and IL-17A after restimulation than that showed by CD4+ T cells isolated from lungs of WT mice at 3 weeks post-infection (w.p.i.)." (PMID 30133544, 2018). "We observed that infection with the fbp1Δ mutant induced enhanced differentiation of IFN-γ-secreting Th1 cells and IL-17A-secreting Th17 CD4+ T cells." (PMID 29317510, 2018). "Depletion of IL-17A significantly increased T-bet expression in γδ T cells and improved recovery from acute IVA infection." (PMID 30116753, 2018). "Although mRNA levels of all these cytokines reduced in RV-infected mice with COPD phenotype, the levels of CXCL-1, CXCL-10, CCL3, TNF-α, IL-17A and IFN-γ remained high up to 14 days post-infection." (PMID 29975735, 2018). "Absolute numbers of IL-17A-expressing MAIT cells increased 200-fold from baseline in acute infection and remained 27-fold increased even after resolution of infection." (PMID 30135490, 2018).
infection (continued). "To investigate lymphocyte activity after infection, we quantitatively determined the presence of IL-2, IFN-γ, TNF-α, IL-4, IL-5, IL-17A, IL-12p70, and IL-22 in mouse sera at day 3, 5, 7, and 9 post-infection; the sera of healthy mice were used as controls." (PMID 30564216, 2018). "The mRNA and protein expression levels of IFN-γ, IP-10, and IL-17A induced by PPD-B, CE, PET, or PBS were measured by real-time PCR and ELISA before injection and at 6, 26, 30, and 58 weeks post-infection." (PMID 29560355, 2018). "The level of IFNγ was similar after all infections; IL-1β was the highest in PEC after cps1-1 and in spleen after ME49; IL-17A was increased after cps1-1 and ME49 in PEC; IL-10 was increased after RH and ME49 in spleen." (PMID 27721814, 2016). "On day 250 post‐infection, the expression levels of IFN‐γ and TNF in the lungs of IL‐17A KO mice were significantly lower than those of wild‐type C57BL/6 mice." (PMID 27980775, 2016). "This context-dependent regulation (in absence vs in presence of infection) indicates that the preconditioning by GLs acts at a level other than the effector/mediator molecules MPO and IL17A (e.g. at the level of sensors or adaptors)." (PMID 27164990, 2016). "In our model, IL-17A secretion is also detected in lesions and draining LNs of LRV1- L. g infection but is significantly up-regulated in response to LRV1." (PMID 27658195, 2016). "However, neutralization of IL-17A alone or in combination with IFN-γ caused a 1.85 log10 (p = 0.019) and a 1.66 log10 (p = 0.0002) CFU increase, respectively, in kidneys of mice that survived the infection compared to survivors injected with isotype-matched control antibody." (PMID 26812180, 2016). "Histopathology analysis of H&E sections prepared at day 14 post-infection demonstrated a modest increase in inflammation in the vaginal lumen and epithelium of WT mice infected with M28 GAS compared with IL-17A−/− mice (arrows)." (PMID 27241677, 2016). "On days 30, 60, or 90 after the infection, a similar level of IFN‐γ producing cells in pulmonary lymphocytes was observed in the wild‐type C57BL/6 and IL‐17A KO mice in response to PPD stimulation." (PMID 27980775, 2016). "On day 60 after infection, the bacterial burden in the lungs of the TCR Cδ KO mice was significantly higher than that of the wild‐type mice, just as observed on the IL‐17A KO mice." (PMID 27980775, 2016). "Since this IL-17A response was lower in individuals from the Central region, who had had more rounds of MDA, our data indicate that such lowered infection pressure influences bystander responses to Plasmodium-derived antigens." (PMID 25889652, 2015). "A distinct subset of IL-17A producing CD8+ T cells, Tc17 cells, also play a role in defense against infections and tumors." (PMID 26367276, 2015). "In contrast, serum IL-17A levels were unaltered early during ETEC infection, while in the intestinal tissues a downregulated IL-17A mRNA production 7 days post infection was observed." (PMID 26490738, 2015). "They demonstrated that this protection was mediated by antibody and IL-17A and inhibited by IFN-γ as shown by antibody transfer to naive mice and neutralization of IL-17A or IFN-γ prior to infection, respectively." (PMID 26060995, 2015). "At day 7 post-infection, a significant proportion of CD4+ T cells isolated from the spleen of dnRara mice were IL-17+ or dual IL-17A+IFN-γ+ with a trend toward reduced frequency of IFN-γ+ cells." (PMID 25769610, 2015). "The IL-17A and IFN-γ secretion in the culture supernatant from spleen cells was analyzed and found to be elevated in immunized compared to unimmunized infection controls." (PMID 26168305, 2015). "We showed that the infection significantly suppressed OVA-induced eosinophilic airway inflammation through enhancing the level of IL-10 and down-regulation of IL-17A." (PMID 25409540, 2014).
infection (continued). "On day 8 post-infection, cells were collected and stained for extracellular expression of CD4 and CD25, and intracellular expression of IFN-γ, IL-4, IL-17A, and Foxp3." (PMID 24918929, 2014). "In contrast, we observed significantly less production of IL-12p40, IL-12p70, IL-1α, IL-1β, IL-17A, CXCL1, CCL2 and CCL5 in the lungs as the infection progressed." (PMID 25119981, 2014). "In a human infection model, carriage of S. pneumoniae increased the prevalence of CD4+IL-17A+TNF+IFN-γ+ Th cells in lungs and blood, as compared to non-carriers." (PMID 25119879, 2014). "The infection induced a significant increase of IL-4 and IL-10 in serum and the culture of splenocytes, whereas, OVA induced a significant increase of IL-17A in serum and splenocyte supernatants compared with in the PBS control mice." (PMID 25409540, 2014). "Results of ICS indicate a significant increase in IFNγ- and IL-17A-producing Prn-, FHA-, and Ptx-specific CD4+CD44+ T-cells after infection." (PMID 25137043, 2014). "Th17 cells produce well-known soluble molecules such as IL17A, IL17F and IL21 which are important for neutrophil recruitment, infection clearance and delivery of antimicrobial peptides." (PMID 25495206, 2014). "At both 17 and 48 hours after infection, 12 cytokines were elevated (G-CSF, M-CSF, IFN-γ, IL-1α, IL-1β, IL-12p70, IL-15, IL-17A, IP-10, MCP-1, MIG, and MIP-1α) in infected mice compared to placebo-inoculated mice." (PMID 23520553, 2013). "Th17 cells exert their biological effects via the secretion of IL-17A, IL-17F, IL-6, IL-22 and TNF-α, which signals neutrophils to move towards the site of inflammation and play an infection-fighting role in the early stage of the immune response." (PMID 23403648, 2013). "Simultaneous treatment with anti-IL17A and GW9662 (1 μM) resulted in significant differences in body weight beginning on day 3 post-infection." (PMID 23469071, 2013). "This is the first study, to our knowledge, to demonstrate expression of both IL-17A and IL-17F in the same CD4+ T cell in a human infection." (PMID 23451159, 2013). "RSV infection significantly increased the absolute numbers in the lungs of IL-17A producing CD4+ T cells, DN T cells, and NKT cells at 2 days post infection." (PMID 24194936, 2013). "Since JNK1 has a role in these infection paradigms and JNK1 −/− mice had a trend towards decreased IL-17A production, the role of JNK1 in IL-17A signaling was investigated." (PMID 22514650, 2012). "Our results show that CD4+ T cells from mice immunized with DnaK+Tul4+GPI responded to DnaK and Tul4 stimulation by producing IFN-γ, IL-10 and IL-17A; and both antigens are processed and presented to CD4+ and CD8+ T cells upon FT LVS infection." (PMID 23209745, 2012). "Following multiple infections, most of the CD4+CD44Hi2W:I-Ab+ T cells had elevated levels of intracellular IL-17A." (PMID 21966268, 2011). "Using this system we detected robust production of IL-2 to QE65 prior to gluten challenge or infection, and strong trends for production of IFN-γ and IL-17A produced in response to QE65." (PMID 21949691, 2011). "In our model, infection of mice with an IFN-γ-producing C. neoformans strain, H99γ, leads to increased production of IL-17A, resolution of the acute infection, and protection against challenge with wild-type C. neoformans." (PMID 21359196, 2011). "Intranasal infection with LVS, which induces IL-17A expression in pulmonary lymphocytes, entailed accumulation of IL-17A in the BALF (Figure 4Aleft) that reached its peak in days 3–4." (PMID 20585449, 2010). "Next, mice were infected with 100 CFU (0.1×LD50) and treated with neutralizing anti IL-17A antibodies or PBS on the day of infection, and again seven days post-infection." (PMID 20585449, 2010). "During infections, the balance between IFN-γ and IL-17A/F cytokines represents the balance between a Th1 and a Th17 response." (PMID 20885956, 2010).
infection (continued). "Infections with T. borreli and T. carassii lead to an increase of IFN-γ2 gene expression whereas IL-17A/F2 gene expression was only observed during T. carasssii infections." (PMID 20885956, 2010). "IL‐17A was positively correlated with the maximum amplitude of anti‐ZIKV IgG response, and IL‐21 was positively correlated with the maximum seroneutralization titers, both in the early and late stage of infection." (PMID 41556482, 2026). "However, on day 7 post-infection, levels of the pro-inflammatory cytokines TNF-α, IL-6, and IL-17A significantly decreased." (PMID 41236498, 2026). "We did not observe substantial Il17a expression in lungs of mice at the early time points analyzed here, nor was the Il17-expressing T cell cluster observed in our scRNA-seq data differentially abundant in the two mouse strains during infection." (PMID 40986319, 2025). "Second, the importance of IL-17F during craniotomy infection remains an open question since the cytokine was absent in Il17a/f–/– mice, whereas only IL-17A was neutralized in Ifng–/– animals." (PMID 39989461, 2025). "We noted that the IL-17 signaling pathway and the JAK–STAT pathway were enriched in the Kyoto Encyclopedia of Genes and Genomes (KEGG) analysis, suggesting that the Th17 cell/IL-17A signaling pathway is important in PmCQ2 infection." (PMID 41402924, 2025). "The evasion of fungal immune control mechanisms with down-regulated Th1 (IFN-γ, TNF-α, and IL-2) and Th17 T cell cytokines (IL-17A) and CXCR3+ T cell chemoattractant chemokine (CXCL10) responses, allows more vigorous replication of Cryptococcus and overwhelming infection." (PMID 39928682, 2025). "This suggested the involvement of both IL-17A and IFN-γ in regulating infection." (PMID 39989461, 2025). "Conversely, IFN-γ receptor 1 (IFN-γR1; CD119) blockade in Il17a/f–/– mice exacerbated infectious burdens in the brain and galea compared with isotype-treated Il17a/f–/– animals confirming the cooperativity between the 2 cytokines and a dominant role for IFN-γ in infection containment." (PMID 39989461, 2025). "Notably, the pro-inflammatory factor IL17A and signaling factor ERK1/2 were among the top regulators affected by the infection." (PMID 41227320, 2025). "To ensure that the increase in Th17s and IL-17A was not simply a consequence of infection with any attenuated Mtb mutant, we evaluated responses during infection with MmpL4 deficient (ΔmmpL4) bacteria." (PMID 40463021, 2025). "LTA -+252 and CCC, TNFA-308 and CCC, IL10-819 rs1800871 and CCC, TLR4 haplotype D229G/T399I with protection from CCC, TIRAP S180L (rs8177374) and rs8177376 (strong linkage disequilibrium) with CCC, IL18 rs360719 and infection, IL17A rs4711998 and infection, TGFB1+10 rs1800470 with infection." (PMID 40297326, 2025). "By day 3, the increase in fungal load in liver had a strong negative correlation with the proinflammatory cytokine IL-17A (−0.85), which suggests the resolution of this infection, since on day 7 no fungal load was detected in the infection by R. pusillus." (PMID 41156648, 2025). "Strikingly, a significant increase in IL-17A expression was measured in lung tissue from mice transferred to lung CD3+γδ T cells compared with other groups, whereas no significant increase in IFN-γ expression was observed post infection." (PMID 39556597, 2024). "Infection of Tcrd-green fluorescent protein (GFP) mice pretreated with an anti-γδ TCR antibody GL3 to induce γδ TCR internalization resulted in much reduced proliferation and IL-17A response from γδ T cells (as identified by the GFP expression)." (PMID 38227652, 2024). "Furthermore, we observed a significant increase in TNFα, IL-1α, IL-2, IL-3, IL-4, IL-9, IL-10, IL-12 (P70), IL-17A, and CCL5 on day 4 post-infection in murine macrophages." (PMID 39038037, 2024).
infection (continued). "Strikingly, a significant increase in IL-17A expression was measured in lung tissue from mice transferred to lung CD3+CD4+ T cells compared with other groups, whereas no significant increase in IFN-γ expression was observed post infection." (PMID 39556597, 2024). "Our results showed low gene expression of IL-17A in normal non-infected lungs, with infection with either strain increasing its expression." (PMID 39024223, 2024). "In PCLS, where neutrophils are scarcely present, an increased expression of pro-inflammatory cytokines and chemokines related to neutrophil recruitment and activation such as CXCL1, CCL3, or IL-17A was measured, particularly in PCLS of old mice upon infection with D61." (PMID 38178102, 2024). "In our case of H. pylori infection, we identify a novel ANGPTL4 regulating cytokine, IL-17A, which exerts synergistic effects on the induction of ANGPTL4 by activating the NF-κB signaling pathway, where its pathway is similar to other pathogen infection." (PMID 39022746, 2024). "Additionally, a substantial increase in IL-17A, CCL11 and IL-3 were observed in the plasma of c-Flip+/–mice on day 2 and day 6 post-infection." (PMID 39038037, 2024). "The characteristics of natural infection were confirmed not only in terms of CD4+ TRM cell response, but also in terms of cytokine response; IFN-gamma and IL-17a responses in MV group were equal or superior to the control and DTaP vaccinated groups after challenge." (PMID 38276680, 2024). "As expected, IFN-γ- but not IL-4- or IL17A-producing T cells increased significantly in the popliteal lymph node of all groups over the course of infection as the adaptive response was established." (PMID 39076982, 2024). "However, the expression level of the IL-17A gene was comparable between muMT mice and WT mice during ETBF infection." (PMID 38203534, 2023). "In addition, we observed that both Il17af−/− and AdipoqCre × Il17rafl/fl mice had a higher food intake over the course of infection compared to C57BL/6 controls, suggesting that IL-17A signalling regulates both bodyweight and food intake." (PMID 37923768, 2023). "In chickens, infection with a vvMDV-RB1B virus led to a significant increase in IL-17A expression at 4 dpi with no changes at 10 dpi and a significant reduction at 21 dpi compared to control chickens." (PMID 37631976, 2023). "Consistent with the role for IL-17A, we observed that removal of CD4+ T cells or macrophages and neutrophils (individually or double depleted) from vaccinated mice just prior to infection rendered them unable to control infection." (PMID 37749129, 2023). "However, BA.5 and its parental strain, B.1.1.529, infection leads to the similar frequency of IFN-γ, IL-17A, IL-10-producing CD4+ T cells as well as IFN-γ, IL-10-producing CD8+ T cells in BALF." (PMID 37704701, 2023). "The function and expression of IL-17A in the avian lung mucosal tissue following infection with MDV have not been previously defined." (PMID 37631976, 2023). "Together, our results suggest that IL-17A/F potentially regulates bodyweight by altering food intake in male mice during infection, but not female mice." (PMID 37923768, 2023). "IL-17A is elevated in patients with CLAD and also in the setting of acute rejection and infection." (PMID 37937643, 2023). "T4 preinfected mice were treated with anti-IL-17A antibodies or the isotype control antibody on days −1, 0, and 1 by intraperitoneal injection and intranasally on day 0 during T4 challenge following PR8 infection." (PMID 37222516, 2023). "In our study there was an important increase in pro-inflammatory cytokines (IL1β, IL6, TNFα, IL18, IL23) upon infection in all the groups analyzed in comparison with age-related control samples, as also seen for the immunoregulatory cytokines IL10 and IL17A, and for Th1 IFNγ NLF." (PMID 36561744, 2022).